APOH (apolipoprotein H)
Diseases named in the same sentence as APOH in open-access papers (continued):
Sharing a sentence is not in itself a finding about the gene and the disease.
psoriasis (1 paper, 2025). An autoimmune condition characterized by red, well-delineated plaques with silvery scales that are usually on the extensor surfaces and scalp. "While limited prior research has primarily focused on apolipoproteins such as ApoA1, ApoA2, ApoB, ApoC1, ApoC3, and ApoE in psoriasis, our study uniquely extends this scope by also evaluating ApoD, ApoH, and ApoJ in this patient population for the first time." (PMID 40137160, 2025). "The aim of this study was to evaluate the potential associations between serum concentrations of apolipoproteins (ApoA1, ApoA2, ApoB, ApoC1, ApoC3, ApoD, ApoE, ApoH, and ApoJ) and various clinical and biochemical markers in patients with psoriasis." (PMID 40137160, 2025). "This suggests that while ApoH may play a role in metabolic and inflammatory processes, its direct contribution to psoriasis severity remains unclear." (PMID 40137160, 2025). "While ApoA1 and ApoB in psoriasis have been the primary focus of research due to their established roles in lipid metabolism and cardiovascular risk, other apolipoproteins, such as ApoA2, ApoC1, ApoC3, ApoD, ApoE, ApoH, and ApoJ, have not been widely studied in psoriasis." (PMID 40137160, 2025).
rhinitis (1 paper, 2022). An inflammation of the mucous membrane lining the nose, usually associated with nasal discharge. "Both APOH and SERPINB3 are upregulated in AR, suggesting that APOH may be involved in an upregulated state in rhinitis, while SERPINB3 acts at different stages of pathogenesis." (PMID 35628512, 2022).
small cell lung carcinoma (1 paper, 2024). Small cell lung cancer (SCLC) is a highly aggressive malignant neoplasm, accounting for 10-15% of lung cancer cases, characterized byrapid growth, and early metastasis. "In both small cell lung cancer (SCLC) and NSCLC, plasma-derived MUC5B, SELL, and APOH have been shown to be potential biomarkers for the diagnosis of brain and liver metastasis." (PMID 38814362, 2024).
Vogt-Koyanagi-Harada syndrome (1 paper, 2024).
tumor (22 papers, 2012 to 2025). "IL-36G and APOH have also been associated with different types of tumour development and progression." (PMID 36065314, 2022). "Consistently, some previously reported genes associated with tumor progression, such as APOH and KRT19, were also gradually upregulated with the development of pseudo-time trajectories." (PMID 36386204, 2022). "ALB and APOH, frequently altered in HCC, contribute to metabolic reprogramming, a hallmark of tumor progression." (PMID 40307890, 2025). "The levels of APOA1, APOH, HEP2, GELS, PZP and PEDF were associated with neoadjuvant pathological tumor (ypT) stage." (PMID 35945555, 2022). "Other evidence suggests that CXCL6 and APOH are potent oncoproteins that promote tumor growth." (PMID 37161430, 2023). "Interestingly, only APOH was downregulated but other 7 ARGs were upregulated in the tumor samples, compared to the normal samples." (PMID 35836112, 2022). "Some of these proteins are key components of cell-cell or cell-matrix adhesion and includes annexin and integrins such as ANXA1, ANAX2, ITGB1, ITGA3, FN1, CTNNB1, APOH which interplay may activate exosome and leukocyte adhesion to tumor cells to limit tumor growth." (PMID 30111323, 2018). "The hub genes in nontumour tissues are GADD45A and IL-36G, while the hub genes in tumour tissues are POSTN and APOH." (PMID 36065314, 2022). "Augmented APOA1 reflects its potential role in driving therapeutic resistance and disease progression by reprogramming the lipid metabolic network of tumor cells; APOB, APOC3, and APOH may function like APOA1." (PMID 39318189, 2024). "While the comparison of expression data between tumor and normal samples showed that 8 out of 36 ARGs were significantly differentially expressed, including CCND2, CXCL6, KCNJ8, LPL, SERPINA5, SLCO2A1, VTN, and APOH." (PMID 35836112, 2022). "However, the role of exosomal MUC5B, SELL and APOH in tumor metastasis has not been reported, and the mechanism of their involvement in tumor metastasis remains to be further explored." (PMID 37770976, 2023). "Moreover, APOH can bind to lipopolysaccharide and activate NF-KB through TLR4 pathway, thus affecting the metastasis and invasion of tumor cells, which may be one of the potential mechanism of its involvement in tumor metastasis." (PMID 37770976, 2023).
infection (17 papers, 2011 to 2024). The state of being infected such as from the introduction of a foreign agent such as serum, vaccine, antigenic substance or organism. "We have recently shown that Plasmodium berghei (Pb) EXP1 binds to host Apolipoprotein H (ApoH) during the hepatic phase of infection and that this interaction plays a pivotal role throughout parasite development inside liver cells." (PMID 31364224, 2019). "The clearance phenomenon could depend on the presence of free active form of the plasmatic ApoH in the organism resulting in different possible pathological consequences of the infection." (PMID 26502286, 2015). "The causes of the reduction of ApoH levels in infections are not well established yet." (PMID 39176097, 2024). "Various soluble proteins of the innate immune system such as C-reactive protein (CRP), ferritin, DNase-I and apolipoprotein H (ApoH) could play an important role, both systemically and locally, in the early stages of infection, to contain it, until a specific response is developed." (PMID 39176097, 2024). "This was confirmed at the protein level, as infection decreased the amount of secreted AHSG and apolipoproteins APOA1, APOE and APOH, in both HepG2 and Huh7 conditioned media, as well as of APOB, APOC3 and SERPINF2 in Huh7." (PMID 34858876, 2021). "Altogether, these data lead us to hypothesize that ApoH could play a pivotal role in the evolution of HCV infection, either favouring or inhibiting the infection." (PMID 26502286, 2015).
cancer (16 papers, 2011 to 2025). A tumor composed of atypical neoplastic, often pleomorphic cells that invade other tissues. "Our findings underscore the critical role of serum protein APOH in the inhibition of ferroptosis and indicates potential therapeutic applications in treating cancer and diseases associated with ferroptosis." (PMID 39353906, 2024). "Among them, five targets (APOH, CD14, ICAM1, LRG1 and SERPINC1) were reported to be associated with other cancers or prognostic significance." (PMID 34199928, 2021). "Dendron‐coated liposomes were found to interact with specific proteins of the blood serum and plasma proteins such as vitronectin and ApoH, which could promote uptake into cancer and mesenchymal stem cells." (PMID 31943635, 2020). "This analysis identified several hub genes, including APOH, APOB, APOA1, and APOA2, which play significant roles in cancer progression." (PMID 39399493, 2024). "APOC3, APOH, HPX, and FGB expression levels were highest in HCC and were greater in normal tissues than that in cancer tissues." (PMID 35449866, 2022). "IPA analysis indicated that pathways of LXR/RXR activation and FXR/RXR activation were most significantly activated, in which APOH, CLU, and ITIH4 were involved in cancer, organismal injury and abnormalities, and reproductive system disease." (PMID 33299887, 2020). "The expression levels of APOC3, APOH, HPX, and FGB were the highest in HCC and were higher in normal tissues than in cancer tissues." (PMID 35449866, 2022).
cardiovascular disease (7 papers, 2011 to 2023). "Furthermore, we found that the polymorphism of the Apolipoprotein H (APOH) gene is associated with elevated levels of lipoprotein (a), an independent risk factor for cardiovascular disease." (PMID 38203557, 2023).
immune disorders (2 papers, 2015 to 2023). "APOH (Apolipoprotein H) and IFNAR1 (Interferon Alpha, Beta, Omega Receptor) are involved in immune disorders." (PMID 25945798, 2015).
APOH also shares sentences with these, for which no sentence is quoted: Stroke (16 papers); Thrombocytopenia (15); Hypertension (11); ischemic stroke (8); myocardial infarction (7); coronary artery disease (6); endothelial dysfunction (6); infectious disease (6); lupus nephritis (6); thromboses (6); Infertility (5); leprosy (5); preeclampsia (5); anticoagulant (4); cerebral infarction (4); coagulopathies (4); Insulin resistance (4); migraine (4); venous thromboembolism (4); acute coronary syndrome (3); acute myocardial infarction (3); atopic dermatitis (3); chronic kidney disease (3); epilepsy (3); Headache (3); heart disease (3); ischemia (3); Miscarriage (3); periodontitis (3); thromboembolic disease (3).
A further 121 diseases each share a sentence with APOH in 2 papers or fewer.